KIT (KIT proto-oncogene, receptor tyrosine kinase)
Diseases named in the same sentence as KIT in open-access papers (continued):
Sharing a sentence is not in itself a finding about the gene and the disease.
melanoma (continued). "Although alterations in KIT were identified in only 3% of all melanomas, they were frequently (28–39%) detected in melanoma arising from CSD skin, acral and mucosal sites." (PMID 33233603, 2020). "We performed a pharmacodynamic study during a phase II clinical trial with nilotinib in KIT-altered melanoma, and showed that the expression of growth factors, such as FGF2, was significantly high at baseline and reduced during nilotinib therapy in responders." (PMID 32344828, 2020). "In high-risk operable or in inoperable stage III and IV melanoma, the most frequently mutated genes are BRAF, NRAS, and c-KIT." (PMID 32054005, 2020). "Consistent with mRNA expression, we found that the expression of CXCL8 and THBS1 protein in metastatic melanoma was significantly higher than that of primary melanoma, while the expression level of KIT was lower." (PMID 32894090, 2020). "In c-KIT-mutant melanoma, several RTK inhibitors have been tested in the clinical space, with comparable overall response rates (ORR) reported for imatinib (23.3%) and nilotinib (26.2%), and slightly lower rates for dasatinib (18.2%)." (PMID 32517051, 2020). "ERK and MEK phosphorylations were previously assessed using immunohistochemistry in eight samples from a phase II clinical trial with nilotinib in KIT-altered melanoma." (PMID 32344828, 2020). "While in NRAS- or BRAF-mutant melanomas, there are increased levels of KIT promoter hypermethylation." (PMID 32825562, 2020). "Although KIT is expressed in some melanomas, as the disease progresses from the superficial stage to infiltration and then to the metastasis stage, the loss of KIT expression indicates that KIT has tumor suppressive function." (PMID 32894090, 2020). "In some subsets of melanomas, the activating mutations in NRAS, PIK3CA and c-KIT were also related with the hyper-activation of Akt49,50." (PMID 32968045, 2020). "Many inhibitors, developed to block KIT and other tyrosine kinase receptors (RTKs), were analyzed in different clinical trials for melanoma such as imatinib, sunitinib, dasatinib, and nilotinib in combination with chemotherapy and immunotherapy." (PMID 33036192, 2020). "Exon 8 is only involved in AML and mastocytosis, while exon 9 is a relatively rare mutation site of KIT in GIST and melanoma." (PMID 31848942, 2020). "Approximately 10% of mucosal melanomas harbor activating mutations in the BRAF gene and another 25% have somatic mutations or amplification of the tyrosine-protein kinase KIT." (PMID 32850452, 2020). "The most promising compound was able to stabilize G-quadruplexes that formed in the promoter regions of two target genes relevant to melanoma, KIT and BCL-2." (PMID 31635389, 2019). "Some of these DEGs had been investigated previously, including CDK2, AKT1 and KIT, which have been widely accepted as oncogenes in melanoma." (PMID 30385854, 2019). "Dog melanoma genes have the same mutations or aberrant expression as human melanoma genes, BRAFV600E, NRAS (Q61), PTEN, and KIT." (PMID 31569419, 2019). "In this analysis BRAF, KIT, NRAS, and PIK3CA mutations were examined by next generation sequencing (NGS) in 446 melanomas in a clinical diagnostic setting." (PMID 31277584, 2019). "Treatment with KIT inhibitors resulted in a trend toward improved response in melanoma patients, with response rates of approximately 20%." (PMID 31398831, 2019). "BRAF and NRAS-mutated melanomas showed a significantly lower incidence of coexisting mutations of different genes (10 and 8.1%, respectively) as compared to PIK3CA, HRAS and KIT-mutated melanomas (75, 67 and 36%; all P < .001)." (PMID 31277584, 2019). "We then assayed the phosphorylation of KIT in a melanoma cell line (MEL526) that endogenously expresses KIT upon stimulation with SCF." (PMID 30931942, 2019).
melanoma (continued). "Furthermore, besides SF3B1 and KIT mutations, other variants have been described in the context of mucosal melanoma, including amplifications of CCND1, MDM2 and KRAS, however this was not assessed this cohort and could represent a source of additional driver eventsin this cohort." (PMID 30847022, 2019). "Melanomas with wild-type BRAF likely have mutations in the upstream proteins of the MAPK pathway, such as NRAS or KIT." (PMID 31890008, 2019). "Partial responses to KIT inhibitors have been observed in less than 20% of patients with acral, mucosal and chronically sun-damaged melanoma patients, reporting a median overall survival of 46 weeks with imatinib and 7.5 months with dasatinib." (PMID 31683701, 2019). "We propose a restricted panel for BRAF, KRAS/NRAS, KIT, CCDN1, and CDK4 mutations in the routine diagnostic test in order to better classify the SNM subtypes of melanoma." (PMID 31581559, 2019). "Low levels of KIT expression have been widely described in most cases of cutaneous melanoma, especially in BRAFV600mut melanoma, due to the endogenous activation of MAPK activation by BRAF mutations." (PMID 31426590, 2019). "Acral and mucosal subtypes of melanoma are predominant in the Japanese population, and the overall detection rates of BRAF, NRAS, and KIT mutations are approximately 30%, 12%, and 13%, respectively." (PMID 30675668, 2019). "KIT mutations commonly occur in GISTs, mastocytosis, CBF AML, and less commonly in melanoma, germ cell tumors and other malignancies." (PMID 29910466, 2018). "The clinical testing of imatinib in patients with melanoma, AML or MCL has been reported; however, the responses have been limited to a subset of patients carrying mutations in the c-KIT gene." (PMID 30404198, 2018). "This is particularly true for BRAF(V600) mutant disease and to a lesser extent for KIT mutant melanoma." (PMID 30405888, 2018). "Other gene mutations in melanoma include NRAS, GNAQ and KIT, estimated to be present in 13–25%, 1.3% (but much more in uveal melanoma) and 2–8% (but more in acral/mucosal subtypes) of melanomas respectively." (PMID 29100459, 2017). "KIT copy number variations are described in melanoma, especially in acral (27.3%) and mucosal (26.3%) melanoma, in glioblastoma multiforme and in intimal sarcoma." (PMID 29312620, 2017). "Nearly 15-30% of mucosal melanomas in the head and neck region harbor activating mutations in BRAF and KIT." (PMID 28404968, 2017). "Assessment of antitumor activity of this combination in the KIT-mutant melanoma population is being evaluated." (PMID 28428884, 2017). "In melanoma, validated drug targets with companion diagnostic utility now include BRAF and c-KIT, as these are driver oncogenes in which activating mutations occur and can be targeted by tyrosine kinase inhibitors (TKIs)." (PMID 28228113, 2017). "Lovly and coworkers have developed a melanoma-specific multiplex mutational profiling assay to detect the 43 recurrent mutations occurring in 6 genes frequently mutated in melanomas: BRAF, NRAS, KIT, GNAQ, and GNA11." (PMID 29156643, 2017). "Recently, some therapies targeted against BRAF mutations (Vemurafenib, Dabrafenib), KIT mutations (Imatinib) and inhibitor of MEK1 and MEK2 (Trametinib) showed good results in advanced stage melanoma." (PMID 29069859, 2017). "In keeping with published studies, there were frequent mutations of BRAF and NRAS in melanoma; BRAF, EGFR, KRAS, and STK11 in NSCLC; APC, BRAF, KRAS, and PIK3CA in CRC; KIT and PDGFR3A in GIST; and CTNNB1 in other tumours (desmoid fibromatosis)." (PMID 28196074, 2017).
melanoma (continued). "Using our in vivo xenograft model of early melanoma, we tested the systemic administration of the small molecule KIT inhibitor nilotinib to prevent melanoma development and horizontal spread." (PMID 27322141, 2016). "In the present work, we demonstrated that mutant KIT signaling in melanoma cells and melanocytes, a condition affecting 5-7% of all melanomas, accelerated their horizontal dispersion from the core lesion to the surrounding healthy appearing skin." (PMID 27322141, 2016). "To investigate if KIT mutant cells can be used to study in vivo migration, we established a mouse model of human skin reconstructs mimicking early melanoma progression." (PMID 27322141, 2016). "Pharmacological KIT inhibition with dasatinib at a concentration of 10nM also reduced gap closure of the KIT mutant melanoma cell lines WM3211KIT(L576P)." (PMID 27322141, 2016). "OncoFOCUSTM+KIT results for patients with malignant melanoma, NSCLC and mCRC are shown inFigures 1A–C, respectively." (PMID 28163892, 2016). "To conclusion, our study identified mutant KIT as a critical component of a mechanism for migration and spread of melanoma cells." (PMID 27322141, 2016). "In fact, in melanomas, hotspot regions or amplification of KIT, PIK3CA, MITF and CTLA4 are often analyzed." (PMID 26863566, 2016). "One important finding was the discovery of frequent mutations and amplifications of the receptor tyrosine kinase c-KIT (KIT) in acral, mucosal and melanomas of chronically sun-damaged skin." (PMID 27322141, 2016). "We present our results with reference to new insights for the tendency of certain melanoma types to recur after apparently complete excision and discuss the potential therapeutic use of KIT inhibitors to treat early melanoma." (PMID 27322141, 2016). "In melanoma patients, acral, mucosal and melanomas of chronically sun-damaged skin have been found to frequently harbor genetic aberrations affecting KIT." (PMID 27322141, 2016). "Next, we investigated the status of relevant molecules and pathways in melanoma, such as c-KIT and the RAS pathway." (PMID 27057633, 2016). "We describe a patient with KIT-mutant vaginal mucosal melanoma who received sequential targeted, immuno- and chemotherapy." (PMID 27502704, 2016). "A few phase II trials have investigated the efficacy of imatinib for melanomas with an alteration in KIT." (PMID 26784231, 2016). "In this study, we investigated the role of mutant KIT in melanocyte- and melanoma cell migration using KIT mutant lines as well as genetically manipulated murine and primary human melanocytes." (PMID 27322141, 2016). "In recent years, KIT has also been a target of interest in advanced melanoma, as certain subsets of patients appear to harbor activating mutations, predominantly acral and mucosal subtypes." (PMID 26784231, 2016). "Mutations in the c-KIT gene, along with overexpression of RAS in part, considered to be involved in the mechanism of development and progression of melanoma, have been identified in mucosal melanoma, suggesting c-KIT and RAS as a promising molecular target." (PMID 26420268, 2015). "We therefore examined the impact of PLX4032 and MEKi on RHOB expression in wild type BRAF melanoma cells harboring mutations in NRAS (WM1346 and SK-MEL2 cells), KIT (WM3211 cells) or KRAS (WM1791C cells)." (PMID 26098773, 2015). "In melanomas, the MAPK pathway is frequently hyperactivated by mutations in the BRAF gene (approximately 50% of melanomas) but also in NRAS (18%), KIT (9%), HRAS (2%) or KRAS (2%) genes (COSMIC database)." (PMID 26098773, 2015). "The trials of other c-KIT inhibitors such as nilotinib and masatinib in melanoma are currently underway." (PMID 26171394, 2015). "This is even more relevant for acral and mucosal melanomas that should be investigated for both BRAF and KIT mutations at the first step." (PMID 24591764, 2014).
melanoma (continued). "The search for driver mutations in melanoma continues, with the previously identified subtypes involving BRAF, NRAS, KIT, GNAQ, and GNA11 expanded recently to include NF1 and telomerase." (PMID 24743024, 2014). "KIT alterations are rare and found mainly in melanomas on chronically sun-damaged skin, in acral-lentiginous or mucosal type." (PMID 24866436, 2014). "Malignant transformation of melanomas is accompanied by loss of KIT and acquisition of EPO-R and ErbB4, both of which are co-expressed with NGF-R and PD-1 in distinct subfractions of melanoma cells." (PMID 24489649, 2014). "These discoveries have led to the development of inhibitors for BRAF and KIT (C-Kit) signaling, some of which have shown benefit in melanoma patients." (PMID 25393105, 2014). "Activating mutations or gene amplification of the tyrosine kinase receptor c-KIT are present in 10 to 15% of acral and mucosal melanomas." (PMID 24679002, 2014). "This is interesting, since acral-lentiginous type of melanoma with higher frequency of KIT alternations is the more frequent in Asian patients." (PMID 24866436, 2014). "Of 50 patients with melanomas, 24 evaluable patients with KIT-mutant (n = 8), KIT-amplified melanoma (n = 11), or both (n = 5) were treated with Imatinib." (PMID 24963404, 2014). "In contrast, ligand-independent activation of KIT due to oncogenic mutations is associated with several types of cancer such as GIST, seminomas, acute myeloid leukemia, melanomas and systemic mastocytosis." (PMID 24116170, 2013). "It is interesting to note that in the majority of melanomas with mutations in BRAF or NRAS, the expression of c-KIT seems reduced to allow tumor progression." (PMID 24416617, 2013). "No activating mutations were detected in the kinase, juxtamembrane or extracellular domains the KIT gene, consistent with the observation that BRAF and KIT mutation are associated with different subsets of melanoma and are generally mutually exclusive." (PMID 24220097, 2013). "A current clinical trial (NCT01168050) is examining Nilotinib as a first or second line treatment of primary melanoma, stage III unresectable, or stage IV melanomas with c-KIT mutations or amplifications (NILOMEL)." (PMID 23515890, 2013). "Genetic classification of different melanoma subtypes has become very important, especially with the introduction of effective therapies targeting genetic alterations such as BRAF and KIT mutations." (PMID 23694694, 2013). "KIT also mediated cell cycle stimulating activities yet its effect seemed to be restricted to a subset of melanomas." (PMID 24416617, 2013). "Ongoing, is the phase II clinical trial (NCT00470470), investigating Imatinib in patients with unresectable stage III or IV melanoma harboring somatic alterations of c-KIT." (PMID 23515890, 2013). "Down regulation of c-KIT is then likely to be related to D6 anticancer activity on melanoma cells, contributing to inhibit cell-proliferation signals." (PMID 23642048, 2013). "The KIT genotype showed the greatest variability between primary melanomas, lymph node metastases, and CTC." (PMID 22281663, 2012). "The BRAF sequences identified in the CTC were inconsistent with those identified in autologous melanoma tumours in three patients and the KIT sequences were inconsistent in three patients." (PMID 22281663, 2012). "Directing this test to a single disease, 90 of 150 (60%) melanomas from sites throughout the body harbored a mutation tested, including 57, 23, 6, 3, and 2 mutations in BRAF, NRAS, GNAQ, KIT, and CTNNB1, respectively." (PMID 22536370, 2012). "KIT has emerged as an important oncogene in melanoma that has been targeted with KIT inhibitors such as imatinib, nilotinib or dasatinib." (PMID 25562798, 2012). "Molecular classification of melanoma is an emerging theme in melanoma therapeutics, with BRAF and c-KIT mutation status determining novel treatment options." (PMID 21980408, 2011).
melanoma (continued). "Previous mobility shift studies were mostly performed with endogenous c-KIT and Mitf in melanocytes and melanoma cells." (PMID 21887372, 2011). "All patients in this trial had specific mutations in c-KIT and/or amplification of c-KIT as well as acral, mucosal, or chronic sun damaged melanoma (which often demonstrate c-KIT aberrations)." (PMID 21479172, 2011). "Our results reveal novel mechanisms by which c-KIT signaling regulates Mitf, with implications for understanding both melanocyte development and melanoma." (PMID 21887372, 2011). "In melanocytes and melanoma the survival gene BCL2 is transcribed as a consequence of c-KIT- mediated Mitf activation." (PMID 21887372, 2011). "Like ETS-1, c-KIT is directly targeted by miR-221/-222, being involved in normal cell growth and differentiation and repressed in metastatic melanomas." (PMID 21711453, 2011). "There are many additional clinical trials that are testing efficacy of c-KIT inhibitors in melanoma." (PMID 21479172, 2011). "A patient with with a KIT PYDHKWE duplication rectal melanoma demonstrated a significant clinical response after 4 weeks of Gleevec treatment." (PMID 21479172, 2011). "Among 142 upregulated genes in melanoma, many are known to be expressed specifically in melanocytes, including KIT, Melan-A, TYR, TRPM1, EDNRB, DCT, SOX10 and SILV." (PMID 21294715, 2011). "Gel shift experiments showed that TFAP2A can bind an element 1.2 kb upstream of the KIT transcription start site, and expression driven by this enhancer in melanoma cells is lost when the TFAP2 binding sites are deleted." (PMID 20862309, 2010). "The differential distribution of genetic alterations in BRAF, NRAS and KIT among melanoma subtypes according to anatomic sites and sun exposure strongly implicated different molecular pathways involved in tumorigenesis for each subtype." (PMID 20426858, 2010). "Small molecule inhibitors like sorafenib inhibit multiple kinases, for example, B-RAF, C-RAF, VEGFR-2, PDGFR and c-KIT, and sorafenib has shown efficacy as single agent and in combination with chemotherapy in patients with advanced malignant melanoma." (PMID 20224761, 2010). "There is as yet too limited data on the correlative responses of melanomas with FGFR2, PTEN/AKT or KIT mutations." (PMID 19949544, 2009). "c-KIT expression was determined in 44 tissue samples, 35 primary mucosal melanomas, 4 lymph node metastases, 2 skin metastases and 3 local recurrences." (PMID 19018266, 2008). "More recently, in patients with diverse KIT-mutated tumors, sunitinib produced PRs in squamous cell carcinoma but no confirmed responses in the melanoma subset, reinforcing the drug’s variable efficacy." (PMID 41301010, 2025). "However, the therapeutic landscape in KIT-mutant melanoma has proven more complex, with variable response rates to TKIs and emerging data on the potential role of immune checkpoint inhibitors (ICI)." (PMID 41301010, 2025). "Patients with melanoma who developed KIT-mutated tumors received no survival benefit from anti-PD-1 adjuvant therapy compared with interferon treatment or observation in a real-world study." (PMID 39996868, 2025). "However, our recent knowledge on the genetics of cutaneous melanoma is far more complex and identified actionable gene defects such as NRAS, KIT or IDH1 mutations and NRAS mutant melanoma are now in clinical trials." (PMID 40361349, 2025). "KIT mutations are identified in approximately 3% of all melanomas, with the majority occurring in acral (36%), mucosal (39%), and chronically sun-damaged skin (CSD; 28%) melanomas." (PMID 39858514, 2025). "Finally, we identify critical gaps in understanding the mechanisms of resistance, CNS progression, and the immunogenic landscape of KIT-driven melanoma." (PMID 41301010, 2025).